RNU6-1119P (RNA, U6 small nuclear 1119, pseudogene)
Gene: Small nuclear RNA gene on chromosome 5 (100,153,672 to 100,153,779, forward strand). Ensembl gene ENSG00000207077.
Homologues: Orthologues: chimpanzee U6 (100% identical), macaque U6 (89% identical). Paralogues in human: RNU6-15P (88% identical), RNU6-1060P (87% identical), RNU6-17P (87% identical), RNU6-18P (87% identical), RNU6-19P (87% identical), RNU6-310P (87% identical), RNU6-1 (86% identical), RNU6-116P (86% identical), RNU6-1181P (86% identical), RNU6-12P (86% identical), RNU6-13P (86% identical), RNU6-188P (86% identical), and 1287 more.